ART1 (ADP-ribosyltransferase 1)
Description:
Has ADP-ribosyltransferase activity toward GLP1R.
Synonyms: ARTC1; CD296; ART2; RT6
Tractability: Antibody: its Gene Ontology location is reachable by antibodies, with high confidence; UniProt predicts a signal peptide or a membrane-spanning region.
Target class: Enzyme; Transferase
Gene: Protein-coding gene on chromosome 11 (3,645,115 to 3,668,548, forward strand). Ensembl gene ENSG00000129744.
Subcellular location: Sarcoplasmic reticulum membrane
Pathways (Reactome):
Immune System: Alpha-defensins
Gene Ontology:
Molecular function: NAD+ poly-ADP-ribosyltransferase activity; NAD+-protein-arginine ADP-ribosyltransferase activity
Cellular component: plasma membrane; cell surface; membrane; sarcoplasmic reticulum membrane
Genetic constraint (gnomAD): Loss-of-function variants: 30 observed, 27.55 expected, observed/expected ratio (o/e) 1.09, 90% interval 0.81 to 1.48. The upper end of that interval is the gene's LOEUF score, 1.48, which puts it in group 6 of 6, group 1 being the genes least tolerant of losing a copy. Missense variants: 480 observed, 435.17 expected, observed/expected ratio (o/e) 1.1, 90% interval 1.02 to 1.19. Synonymous variants: 201 observed, 180.42 expected, observed/expected ratio (o/e) 1.11, 90% interval 0.99 to 1.25.
Homologues: Orthologues: chimpanzee ART1 (99% identical), macaque ART1 (95% identical), dog ART1 (85% identical), pig ART1 (85% identical), guinea pig ART1 (83% identical), rabbit ART1 (81% identical), rat Art1 (77% identical), mouse Art1 (76% identical), tropical clawed frog art1 (39% identical), zebrafish si:ch211-145b13.6 (17% identical). Paralogues in human: ART5 (31% identical), ART4 (31% identical), ART3 (28% identical).